ATF3 (activating transcription factor 3)
Diseases named in the same sentence as ATF3 in open-access papers (continued):
Sharing a sentence is not in itself a finding about the gene and the disease.
tumor (continued). "In cancer development, ATF3 has been reported to exhibit dual functions such as tumor suppressor or tumor progression, depending on cell context." (PMID 27043582, 2016). "For the drug distribution and ATF-3 IHC analyses, tumor biopsies were collected from all 20 patients in the TPEC." (PMID 25777468, 2015). "The consistent association between ATF3 and MMP2 expression suggests that ATF3 exerts a similar function with MMP2 in some ways, and plays a role in promoting tumor metastasis." (PMID 25872784, 2015). "The study also provided evidence of target engagement in tumor tissue during treatment through the increase in ATF-3 expression in post-dose tumor samples." (PMID 25777468, 2015). "Inhibition of whole-blood 20S proteasome activity and upregulation of ATF-3 in tumor biopsies demonstrated target engagement." (PMID 25777468, 2015). "Scrutiny of the top 30 genes identified a number of novel EZH2 target genes with possible tumor suppressor gene roles, including the ATF3 transcription factor; validated by ChIP-qPCR." (PMID 26304929, 2015). "The growth curves of the xenograft tumors of the nude mice indicated that tumor growth in the cisplatin group and the ATF3-siRNA + cisplatin groups was attenuated in a time-dependent manner; thus, the rate of increase in tumor volume decreased with time." (PMID 25872784, 2015). "Much still remains to be learned about the complex roles of ATF3 in the context of tumor progression." (PMID 25149542, 2014). "Consistently, the present study also showed over-expression of ATF3 suppressed the tumor growth in vitro and in vivo while ATF3 silencing did the opposite, supporting an important role for ATF3 in cell proliferation." (PMID 25149542, 2014). "Immunohistochemical analysis on the subcutaneous tumor tissues also confirmed that MMP-2 was decreased upon ATF3 expression." (PMID 25149542, 2014). "In the Tg(flk1:RFP)is18 transcriptome atf3 expression levels increased significantly in Pretumor and Tumor tissue." (PMID 25485542, 2014). "Both Western blotting analysis on cell lysates and Immunohistochemical staining on the subcutaneous tumor tissues revealed that MDM2 were up-regulated with ATF3 forced expression." (PMID 25149542, 2014). "ATF3 reportedly plays differing roles in the development of tumor, depending on the cell type and context." (PMID 23533526, 2013). "ATF3 is activated in most human cancers either directly or indirectly, which highlights its critical biological function as a tumor suppressor gene." (PMID 24494067, 2013). "The role of ATF3 in malignancy cannot be generalized as either being oncogenic or tumor suppressing; it exhibits properties of both functional classes." (PMID 22768301, 2012). "In fact, in the oncology field, where ATF-3 has been extensively studied, it seems that the cellular context strongly influences its role in cancer development, acting as an oncogene or as a tumour suppressor." (PMID 22769424, 2012). "In some systems, ATF3 appears to function in tumor suppressive pathways, and in particular has recently been associated with induction of apoptosis after treatments that induce lethal levels of DNA damage." (PMID 21304988, 2011). "Two known transcriptional targets of ATF3, Snai1 and Snai2, are also overexpressed in the tumors, and Snail and Slug proteins are found to be located primarily in the nuclei of tumor cells." (PMID 21304988, 2011). "We have found aberrant expression of cytokeratins 5 and 8 in most tumor cells in the BK5.ATF3 model, as well as supra-basal expression of cytokeratins 6 and 10 and several cytokeratins that are characteristic of the inner root sheath of hair follicles." (PMID 21304988, 2011). "Promoters of upregulated genes in tumor were associated with binding sites of cell cycle regulators such as AP1-like factors, STAT, and E2f, of which Atf3, Jun, and E2f3 were significantly upregulated in both transgenic and tumor cells." (PMID 21464922, 2011).
tumor (continued). "The consequences of ATF3 induction result in tumor growth inhibition and suppression of Ras-stimulated tumorigenesis." (PMID 20137089, 2010). "As the tumor cells filled the intramedullary space of the bone, a significant up-regulation of ATF-3 expression also occurred in sensory neurons of the ipsilateral DRG." (PMID 21048940, 2010). "Onconase treatment consistently resulted in up-regulation of IL-24, previously shown to have tumor suppressive activity, as well as ATF3 and IL-6." (PMID 20137089, 2010). "The results show that down-regulation of ATF3 by ATF3-shRNA leads to an increased tumor growth rate, as compared to Luc-shRNA transfected control cells." (PMID 21129190, 2010). "This tumor suppressive effect of ATF3 is also supported by their findings, where transfection of cancer cells with a full-length ATF3 vector suppressed tumorigenicity and invasiveness in vitro and tumor growth in vivo." (PMID 21129190, 2010). "Another possible cell death associated pathway resulting in activation of ATF3 by TRD is the ER stress response pathway, since TRD has been reported to inhibit protein translation in tumour cells at an early stage." (PMID 21034493, 2010). "The impact of ATF3 down-regulation on cancer growth and metastasis were investigated in a subcutaneous tumor model, a model of hepatic tumor growth and in a model of peritoneal carcinomatosis." (PMID 21129190, 2010). "Camptothecin and etoposide, DNA topoisomerase inhibitors, as well as the anthracycline antibiotic doxorubicin have all been shown to induce ATF3 in tumor cells." (PMID 20137089, 2010). "The factors HIF-1α and ATF3 are both induced by hypoxia and other cellular stressors, and both transcription factors regulate the expression of multiple genes during tumor progression and metastasis." (PMID 21129190, 2010). "We next tested the effects of inhibited ATF3 expression on tumor metastasis in vivo in a model of hepatic tumor growth and in a model of peritoneal carcinomatosis." (PMID 21129190, 2010). "The effects of diminished ATF3 expression on tumor growth in vivo were first investigated in a subcutaneous tumor model using HCT116 cells." (PMID 21129190, 2010). "In subsequent hepatic and peritoneal tumor models, we were able to demonstrate a significant increase in tumor burden, cancer dissemination, and tumorigenicity upon further down-regulating ATF3." (PMID 21129190, 2010). "This study identifies the pro-apoptotic factor, ATF3 as a novel target of M344, as well as a mediator of the co-operative effects of cisplatin and M344 induced tumour cell cytotoxicity." (PMID 20828393, 2010). "This suggests that over-expression of ATF3 results in fundamental alterations in the differentiation status of the affected tumor cells, including expression of markers characteristic of multiple tissues and epithelial lineages." (PMID 18808719, 2008). "In all cases examined, the tumor regions that exhibited ATF3 nuclear staining were also positive for cytoplasmic CK5 and CK8 (data not shown)." (PMID 18808719, 2008). "Consequently, this repression inactivates ATF3's tumor-suppressive functions, activating oncogenic PI3K-Akt signaling while suppressing the Hippo pathway." (PMID 42157949, 2026). "Finally, immunoblot analysis of tumor tissues demonstrated significant upregulation of ATF3 in the DSF/Cu group." (PMID 41438581, 2026). "ATF3+ epithelial cells were enriched in pathways related to response to oxygen levels and regulation of protein kinase activity, indicating stress conditions in tumor cells." (PMID 40520021, 2025). "However, ATF3 is expressed in several cell types within PDAC tumours, including epithelial, immune, and fibroblast cell populations." (PMID 41198649, 2025). "To investigate the roles of CCDC86/ATF3 in tumor growth, we conducted in vivo animal experiments." (PMID 40837407, 2025). "This apparent contradiction may be attributed to the divergent roles of ATF3 in tumor cells versus dendritic cells." (PMID 41294838, 2025).
tumor (continued). "Additionally, cardiac remodeling promotes tumor growth, as transverse aortic constriction (TAC) favors primary tumor growth and cardiac dysfunction promotes metastasis through activating transcription factor 3 (ATF3)." (PMID 39846541, 2025). "Together, these analyses demonstrate that multiple core features of wild-type DFFB persister and DTEP cells are present within drug-stressed residual tumours including anastasis, ATF3 and IFN regulation, but that untreated or fully resistant tumours which avoid drug stress lack these features." (PMID 41249572, 2025). "While opposing roles were not based on cell type expression, loss of ATF3 in epithelial cells likely had indirect effects on cell composition of the tumour microenvironment." (PMID 41198649, 2025). "In line with the proposed mechanism, immunofluorescence analysis demonstrated a marked upregulation of ATF3 expression in tumor tissues from Vin-treated mice, supporting the in vivo activation of the P38/MAPK/ATF3 signaling pathway and its role in mediating IL-24 expression." (PMID 40866941, 2025). "Given the highly complex interactions of tumour cells and the microenvironment, understanding the role for ATF3 in these cell types could identify targets for increasing efficacy in PDAC therapy." (PMID 41198649, 2025). "Additionally, our investigation unveiled a potential mechanism whereby CCDC86 activated the ERK signaling pathway through ATF3, thus influencing glycolysis to drive tumor progression." (PMID 40837407, 2025). "For instance, sc-seq has uncovered malignant cell subclusters enriched in genes associated with histone deacetylase (HDAC) inhibitor response (ATF3, CAV1), inflammation (LXN, PGM1), and hypoxia-linked tumor metastasis (WSB1), highlighting their importance in tumor progression." (PMID 41450739, 2025). "However, this pathway needs further discussion because ATF3 sometimes exhibits tumor-suppressive properties." (PMID 39802954, 2024). "In addition, the genes characterizing classical phenotypes of cancer stem-like (ASCL2), hypoxia (WSB1) and apoptosis (ATF3) were all highly expressed in the tumor or stromal region, suggesting cell differentiation programs." (PMID 38729966, 2024). "However, other studies have reported that ATF3 can promote tumor growth and metastasis in breast cancer and cutaneous squamous cell carcinoma." (PMID 39085957, 2024). "Interestingly, Smad4 promoted nuclear translocation of activating transcription factor 3 (ATF3) to activate the p38 mitogen-activated protein kinases signaling pathway by binding to ATF3, inducing apoptosis of neuro-2a cells and inhibiting tumor growth." (PMID 38218852, 2024). "Finally, we assessed the roles of p‐S767/768 in regulating ATF3 expression in vitro and tumor progression in vivo." (PMID 38828688, 2024). "This discrepancy might be explained that increased ATF3 expression is observed only in a subgroup of tumor cells comprising only a few percent of all cells in the tumor and therefore this subgroup could not be identified in bulk sequencing analyses." (PMID 38658567, 2024). "Also, this class of Purinergic genes positively correlates with the expression of various immunomodulatory factors during tumor development and promotes the immune escape of tumor cells through the ATF3-PD-L1 signaling pathway." (PMID 38180750, 2024). "ATF3 is a stress-responsive transcription factor of the basic leucine zipper (bZip) family and is essential for controlling physiological functions such as the cell cycle, tumor suppression, and TLR4 signaling." (PMID 37261340, 2023). "In conclusion, ATF3 was identified as a novel marker of QCCs, and combining conventional drugs targeting PCCs with an option to target QCCs by reducing ATF3 expression levels may be a promising strategy for more efficient removal of tumor cells." (PMID 37833290, 2023).
tumor (continued). "Moreover, inhibiting ADORA1 expression enhances immune evasion of tumor through modulating ATF3-PD-L1 axis, which is the critical biomarker for ICB response in NSCLC." (PMID 37083272, 2023). "In addition, the expression of circSTX6 in tumour tissues was negatively associated with METTL14 and ATF3 but positively correlated with circSTX6‐144aa." (PMID 37877357, 2023). "Besides, the costaining of circSTX6 and ATF3 in HCC cohort‐2 revealed that approximately 85.2% of the circSTX6 highly expressed tumour tissues weakly expressed ATF3, whereas 76.9% of circSTX6 weakly expressed tumour tissues showed stronger ATF3 staining." (PMID 37877357, 2023). "ATF3 is also known as an activator of the tumor invasive potential by up-regulating the expression of the matrix metalloproteinase (MMP) family members (i.e., MMP-1, MMP2, MMP-9 and MMP-13), whose mRNA and protein abundance are correlated with BC invasion and metastasis." (PMID 37447165, 2023). "Activating transcription factor 3 (ATF3) is promoting tumor growth in CRC." (PMID 38033043, 2023). "Furthermore, the most effective analogs were analyzed via qPCR to determine efficacy in modulating expression of two critical tumor suppressor genes, ATF3 and EGR3." (PMID 37947652, 2023). "In addition, regulon specificity score (RSS) analysis also indicated that the Atf3 regulon was the most specific regulon in the day 15 tumor samples." (PMID 36718369, 2023). "Moreover, ablation of ATF3 prevented tumor regression in response to EZH2 and HDAC inhibitors in vivo (light blue line)." (PMID 37104245, 2023). "Serial sections from the same tumor tissues were used for IHC analysis of ATF3 and PD-L1." (PMID 37723150, 2023). "Double IF labeling for PD-L1 and ATF3 in mouse tumor tissues yielded similar results." (PMID 37723150, 2023). "Zfp36, HMOX1, and ATF3 have antioxidant effects and play important roles in tumor progression." (PMID 36835629, 2023). "Importantly, DMI-mediated ATF3 upregulation suppresses IL-17–mediated IκBζ signaling pathway activation, thus ameliorating skin pathological inflammation in vitro and in vivo." (PMID 37261340, 2023). "The expressions of all module genes were significantly discrepant by comparing normal samples with tumor, including three genes (ATF3, IER2, and NNR4A2) downregulated in para‐cancerous compared to normal tissues, which were also low expressed in BC compared to normal samples." (PMID 35037412, 2022). "In addition, ATF3 can play a synergistic anti-tumor role with Epigenetic Drugs and Protein Disulfide Isomerase Inhibitors in tumor therapy." (PMID 35871061, 2022). "ADORA1 Inhibition promotes tumor immune evasion by regulating the ATF3-PD-L1 Axis." (PMID 36291758, 2022). "We found cancer-induced increase in relative Atf3 gene expression in MOC1 males and MOC2 males and females compared to sex-matched sham treated mice as well as a cancer-induced increase in ATF3-IR in MOC2-tumor bearing males only compared to male PID14 sham mice." (PMID 36172037, 2022). "Considering the mRNA regulating effect of miRNA and miRNA regulating effect of METTL1, we screened genes negatively correlated with METTL1 and confirmed tumor suppressor ATF3 was the downstream target of METTL1-modified miR-760, which was confirmed by dual-luciferase reporter assay." (PMID 36396627, 2022). "Additionally, MOC2 tumor growth invoked a substantial injury response in the trigeminal ganglia as defined by a significant upregulation of injury response marker ATF3 in tongue-innervating trigeminal neurons." (PMID 36172037, 2022). "Since MC38 tumor growth was associated with systemic reductions in IENF density, we investigated well-established indicators of neuronal damage at the level of the DRG: elevated macrophage density and increased expression of ATF-3." (PMID 35962398, 2022).
tumor (continued). "In addition, cAMP-dependent transcription factor 3 (ATF3) inhibits tumor cell proliferation by inducing tumor cell apoptosis and functions as an immunomodulator by interacting with nuclear factor κB (NF-κB) and repressing proinflammatory cytokines." (PMID 36291878, 2022). "In addition, across tumor types, this apoptotic sensitivity also depends on the pro-apoptotic function of the activating transcription factor 3 (ATF3) operating through direct transcriptional repression of the pro-survival factor BCL-XL." (PMID 35455435, 2022). "Interestingly, some of these genes (Atf3, chinmo, and chn) have been reported to be involved in tumor growth in Drosophila." (PMID 36222503, 2022). "In addition to the different levels of chaperones that are dependent on HSF1, the inflammatory response mediated by AP1 and ATF3 (regulated by HSF1) can differ from tumor to tumor." (PMID 36010586, 2022). "Consequently, the tumor suppressor role of ATF3 made a further statement that ATF3 was a target gene regulated by METTL1-modified miR-760." (PMID 36396627, 2022). "The role of ATF3 depends on different kind of cancers, acting tumor suppressor or tumor promotor." (PMID 36396627, 2022). "ATF3 expression exhibited significant negative correlation with tumor purity (r = − 0.145, P = 6.92E−03) and slight association with dominant macrophage levels." (PMID 33407456, 2021). "Furthermore, higher expression levels of ATF3, PPP1R15A, PPP2R5B, DDIT3, and BCL10 are associated with better prognosis in HER2+-BC patients, suggesting an overall tumor-suppressive role of the UPR-driven signaling cascade." (PMID 34007022, 2021). "Interestingly, ATF3 can act as an oncogene or as a tumor suppressor gene, depending on the type of tumor and the cellular context." (PMID 33539340, 2021). "Previous studies reported that ATF3 expression was frequently downregulated in several tumor types." (PMID 34728784, 2021). "Functionally, as a tumor suppressor, ATF3 inhibited ccRCC cell growth both in vivo and in vitro." (PMID 33816467, 2021). "In addition to modulating the metabolism, ATF3 was found to play a dual role as an oncogene and tumor suppressor in multiple cancers." (PMID 34571936, 2021). "ATF3 could serve as an oncogene or tumor suppressor gene, which depended on the tumor microenvironment." (PMID 34966780, 2021). "Here we found ASC-J9® could also suppress the PCa progression via an AR-independent mechanism, which might involve modulating the tumor suppressor ATF3 expression." (PMID 33390173, 2021). "ATF3 was down-regulated in BC tissues and negatively correlated with tumour stage, and could suppress BC cell metastasis through the upregulation of GSN-mediated actin remodelling." (PMID 34187252, 2021). "We calculated the normalized expression values (tumor: normal) in our ATF3-induced tumors for each of these intrinsic gene expression sets, and found that only the basal and proliferation gene sets were significantly overexpressed (p = 0.0081 and 0.00019, respectively)." (PMID 33652981, 2021). "Taken together, our results suggest that FOXP3 functions as a novel regulator of ATF3 and that this novel event may be involved in tumor development and progression." (PMID 34768829, 2021). "Colorectal cancer tumor growth and metastasis was found to be enhanced by increased levels of oncogenic piR-1245 which is capable of binding and subsequently suppressing multiple tumor suppressors such as ATF3, DUSP1, and SESN2 by degradation of mRNA." (PMID 33673453, 2021). "Furthermore, ATF3 has been shown to act as a tumor suppressor or oncogene in xenograft models using different cell lines." (PMID 33407456, 2021). "The roles of ATF3 in tumor cells have been intensively investigated in recent years." (PMID 33539340, 2021).